IL2 (interleukin 2)
Diseases named in the same sentence as IL2 in open-access papers (continued):
Sharing a sentence is not in itself a finding about the gene and the disease.
metastatic clear cell renal cell carcinoma (6 papers, 2013 to 2020). "CA9 SNP patients with metastatic clear cell renal cell carcinoma may be associated with better survival and a greater opportunity to response to interleukin-2." (PMID 24349364, 2013). "A phase I/II clinical study targets patients with metastatic clear cell renal cell carcinoma (ccRCC) by treatment with entinostat and high-dose interleukin-2 (IL2) that downregulates forkhead box P3 (Foxp3) expression and function of regulatory T cells (Treg)." (PMID 33117804, 2020). "The RECCORD study included only patients with clear cell renal cancer (80% of our cohort), and included patients on clinical trials and a small number of patients receiving IL-2 or IFN-α." (PMID 32680483, 2020). "IL2-XE114-TNFmut may thus be considered as a promising biopharmaceutical for the treatment of metastatic clear-cell renal cell carcinoma, since these tumors are known to be sensitive to IL2 and to TNF." (PMID 31799191, 2019). "Renal clear cell carcinoma (KIRC), an immunogenic tumor type in which immunotherapies such as IL-2, IFN-α, and nivolumab have shown clinical benefit in a subset of patients, had the second-highest median TIS scores but fairly low mutation load." (PMID 29929551, 2018).
metastatic colorectal cancer (6 papers, 1993 to 2023). "Adding IL-2 to chemotherapy for the treatment of metastatic colorectal cancer improved the objective response rate." (PMID 31731818, 2019). "A clinical trial, the results of which were published in 1995, reported that low-dose interleukin-2 (IL-2) and melatonin prolonged the one-year survival and improved the quality of life in patients with metastatic colorectal cancer (CRC), who progressed despite initial response to 5-FU." (PMID 36759799, 2023). "Forty-four patients with metastatic colorectal cancer were treated, predominantly on an outpatient basis, with subcutaneous IFN alpha-2a and IL-2 three times per week followed by once a week bolus intravenous 5-FU injections." (PMID 8980407, 1996).
myeloid leukemia (6 papers, 2016 to 2025). A clonal proliferation of myeloid cells and their precursors in the bone marrow, peripheral blood, and spleen. "Based on the literature review, this study is the first report to show that WT1 can regulate the RNA expression of IL-2, IL-2RB, and IL-2RG in the myeloid leukemia cells." (PMID 33110919, 2020). "However, the role of the IL-2 signaling pathway in myeloid leukemia cells is largely unclear." (PMID 33110919, 2020). "Using NK92 and IL-2-producing NK92MI cells, we observed that NKp30-mediated cytotoxicity against myeloid leukemia cells such as K562 and THP-1 cells expressing B7-H6, a ligand for NKp30, was severely impaired by IL-2 deprivation." (PMID 38698855, 2024).
osteoporosis (6 papers, 2022 to 2025). A condition of reduced bone mass, with decreased cortical thickness and a decrease in the number and size of the trabeculae of cancellous bone (but normal chemical composition), resulting in increased fracture incidence. "At the same time, the MR results showed that the increase of IL-2 could lead to the occurrence of osteoporosis, and there was a significant causal relationship between them." (PMID 37949959, 2023). "Hallmark-IL2/STAT5 and WNT/β-catenin pathways were upregulated in parathyroid cells of osteoporosis patients." (PMID 40496565, 2025). "Specifically, the total MR Effect size between SNPs of IL-2, IL-7, and osteoporosis were presented by forest plots, the IVW method was used as the main analysis method." (PMID 37949959, 2023). "In addition, the results of RT-qPCR and Elisa experiments verified that the expression of STAT4 was consistent with the previous analysis, and a significant causal relationship between IL-2 and STAT4 SNPs and osteoporosis was found by Mendelian randomization." (PMID 37949959, 2023). "Furthermore, it has been observed that Th2 dominance is related with senile osteoporosis, implying that Th2-type cytokines such as IL-10, IL-6, IL-5, and IL-4 levels rose while Th1-type cytokines such as IL-2,IFN-γ and TNF-α reduced in patients suffering from senile osteoporosis." (PMID 38461235, 2024).
pancreatic adenocarcinoma (6 papers, 2020 to 2025). "In this study, we demonstrate that Nerofe combined with low-dose doxorubicin (ldDox) induces IL-2 expression in human pancreatic adenocarcinoma cells (PANC-1) through activation of the AP-1 transcription factor." (PMID 41459907, 2025). "Two CAR-T cells showed increased release of IFNγ, TNFα, IL-2 and very limited production of IL-6 after stimulated by four EpCAM positive pancreatic adenocarcinoma cells while not by hTERT–HPNE." (PMID 41417221, 2025).
pancreatitis (6 papers, 2008 to 2025). Inflammation of the pancreas. "In pancreatitis, IL-2 acts as a key immunoregulatory factor, significantly promoting the proliferation of Tregs, especially the CD25+CD4+T cell subset." (PMID 39958351, 2025). "The aim of this study wasto investigate the association between early changes (within 24 hours) in theserum IL-2, IL-4, TNFα, and IL-6 concentrations and occurence ofsubsequent pancreatitis complication after ERCP." (PMID 18670651, 2008). "Therefore, precise modulation of IL-2’s immunoregulatory effects is essential in treating pancreatitis and PC to alleviate symptoms and slow disease progression." (PMID 39958351, 2025). "Furthermore, PARP inhibitors have demonstrated effects on reducing pro-inflammatory mediators in the plasma such as TNF-α, IL-1β, IL-2, IL-4, IL-6, IL-12, IP-10, and KC on in vitro models of pancreatitis as well as in vivo models of wound healing injuries." (PMID 33663560, 2021). "Since other leukocyte subsets and various cytokines, such as dendritic cells, IL-2, and GM-CSF, also affected the pancreatitis development in aly/aly mice, it will be interesting to examine the connection between splenectomy and these factors in the further study." (PMID 20369067, 2010).
Q fever (6 papers, 2015 to 2021). A bacterial infection caused by Coxiella burnetii. "The QFS patients show similar levels of IFN-γ and decreased IFN-γ/IL-2 ratio compared to those affected by chronic Q fever." (PMID 34796128, 2021). "For example, it has been observed that an IFN-γ/IL-2 ratio > 11 is strongly suggestive for chronic Q fever." (PMID 34796128, 2021). "It is of interest though that we do see somewhat higher IL-2 responses and a lower IFNγ/IL-2 ratio in the asymptomatic Q fever seropositive control group of our study." (PMID 29804281, 2018). "It was also shown that antigen-specific IFNγ production is a useful tool for diagnosing a previous Q fever infection, and adding antigen-specific IL-2 production helped discriminate chronic Q fever patients from Q fever seropositive controls and QFS patients." (PMID 29804281, 2018). "We propose that the IFN-γ/IL-2 production profile can be used as an additional immunological biomarker for treatment monitoring of chronic Q fever." (PMID 25729380, 2015). "Q fever endocarditis patients had overall higher IFN-γ/IL-2 ratios than the vascular Q fever patients." (PMID 25729380, 2015). "We measured the C. burnetii-specific IFN-γ and IL-2 production in a whole-blood stimulation assay during a period of at least 18 months follow-up of proven chronic Q fever patients." (PMID 25729380, 2015). "Our finding that the IFN-γ/IL-2 ratio declines during successful treatment of chronic Q fever, assuming a decrease in antigen load, is in accordance with these studies." (PMID 25729380, 2015). "The C. burnetii-specific whole-blood interferon-γ (IFNγ) production assay showed promising results in differentiating QFS patients from Q fever seropositive controls and further implementation of an IFNγ/interleukin-2 (IL-2) ratio helped differentiate QFS patients from chronic Q fever patients." (PMID 29804281, 2018). "The present study follows the hypothesis that the IFN-γ/IL-2 ratio will decline during effective treatment of chronic Q fever." (PMID 25729380, 2015). "We studied the longitudinal IFN-γ/IL-2 ratio in fifteen chronic Q fever patients." (PMID 25729380, 2015). "The lower IFN-γ/IL-2 ratio we observed in patients with endovascular infections compared to endocarditis patients suggests that these manifestations of chronic Q fever differ with respect to antigen concentrations; vascular infections might be a more low-grade infection than endocarditis." (PMID 25729380, 2015). "Other cytokines also play a role in Q fever as TNF-α, IL-1-β, and IL-10 as well as IL-2 and the IL-12/IFN pathway does play a role." (PMID 32765448, 2020). "We start by comparing antigen-specific whole-blood IFNγ and IL-2 production in QFS patients who have recovered from their complaints, QFS patients who have persisting complaints, and asymptomatic Q fever seropositive controls." (PMID 29804281, 2018). "To test this, we followed 15 chronic Q fever patients for at least 18 months during antibiotic treatment and performed whole-blood stimulation assays with measurement of IFN-γ and IL-2 on a regularly basis." (PMID 25729380, 2015). "In chronic Q fever, C. burnetii-specific IFN-γ production is higher and IL-2 production is lower than in individuals with past Q fever." (PMID 25729380, 2015). "In addition, after stimulation with C. burnetii antigens, monocytes from Q fever patients produced PGE2, which in turn downregulated T lymphocyte-mediated IL-2 and IFNγ production." (PMID 29390006, 2018). "C. burnetii-specific IFNy, IL-2, CXCL9, CXCL10, and CXCL11 production were tested in ex vivo stimulated whole blood of QFS patients who recovered from their complaints (n = 8), QFS patients with persisting complaints (n = 27), and asymptomatic Q fever seropositive controls (n = 10)." (PMID 29804281, 2018).
Q fever (continued). "Reviewing the results from the current study we can argue that simple measurement of CXCL9 serum concentration may also be of help in distinguishing chronic Q fever from past infection, although its specificity and sensitivity is somewhat lower than the IFN-γ/IL-2 production assay." (PMID 28793883, 2017).
sarcopenia (6 papers, 2022 to 2025). Progressive decline in muscle mass due to aging which results in decreased functional capacity of muscles. "Blood was drawn, and inflammatory biomarkers associated with Sarcopenia (IL-2, IL-4, IL-5, IL-6, IL-8, IL-10, TNF, adiponectin, leptin, resistin, BDNF, sTNFr-1 and sTNFr-2) was analysed." (PMID 37365209, 2023). "Intriguingly, sarcopenia was found to predict the response to Interleukin-2 (IL-2) treatment in metastatic RCC scenarios." (PMID 39568720, 2024). "The results revealed significantly higher expression of genes associated with ERBB, IL-2, IL-4, oxidative stress response and JAK-STAT signaling pathway in the sarcopenia group." (PMID 39026669, 2024). "More specifically, a variety of cytokines, including tumor necrosis factor (TNF)-α, interleukin (IL)-1, IL-2, IL-4, IL-6, IL-8, and IL-10 play a role in the development of sarcopenia." (PMID 36160136, 2022). "Our analysis revealed that the sarcopenia group exhibited upregulation of several immune-related pathways, such as JAK-STAT, ERBB, and IL-2/4 signaling pathways, in comparison to young controls." (PMID 39026669, 2024). "Various cytokines involved in the pathogenesis of sarcopenia have been identified in foreign studies and include TNF-α, IL-1, IL-2, IL-4, IL-6, IL-8, and IL-10." (PMID 36160136, 2022). "The dependent variable (sarcopenia) was a binary classification (0= absent, 1= present), and continuous independent variables included levels of four inflammatory cytokines: IL-2, IL-6, IL-8, and TNF-α." (PMID 40265008, 2025).
SARS-CoV infection (6 papers, 2008 to 2022). "Furthermore, IL-2-encoded DNA vaccine plasmids were designed by Hu and co-workers against severe acute respiratory syndrome (SARS) in 2009." (PMID 35891284, 2022). "During the process of SARS-CoV infection, there was a cytokine storm in patients including IL-1, IL-2, IL-4, IL-6, IL-8, IL-10, IFN-γ, TNF-α and TGF-β1." (PMID 18312678, 2008). "Abnormalities in the production levels of several cytokines such as IL-1, IL-2, IL-4, IL-6, IL-8, IL-10, IFN-γ, TNF-α and TGF -β1 were detected in patients with SARS-CoV infection." (PMID 32917282, 2020).
skin cancer (6 papers, 2018 to 2026). "Additionally, an elevated signaling of Il2/Stat5 in skin tumors is consistent with a recent report stating that Il2 regulates CD8 T cell exhaustion in the tumor microenvironment." (PMID 40282557, 2025).
sleep disorder (6 papers, 2021 to 2025). A change from the patient's baseline sleeping pattern, in the hours slept and/or an alteration/dysfunction in the stages of sleep. "Occupational stress and mental disorders were risk factors for sleep disorder, and that the level of IL-2 was a protective factor for sleep disorder." (PMID 36245869, 2022). "IL-2 (OR = 0.616, 95% CI: 0.433–0.876) was a protective factor for sleep disorders, and the higher the concentration of IL-2, the lower the risk of sleep disorders." (PMID 36245869, 2022). "The lower the IL-2 level, the higher the risk of sleep disorder." (PMID 36245869, 2022). "Low occupational stress and the interaction between mental health and IL-2 may reduce the risk of sleep disorders." (PMID 36245869, 2022). "Sleep disorders are also associated with an increased systemic immune and inflammatory dysregulation, mainly due to hyperexpression of pro-inflammatory mediators and cytokines (e.g., IL-1β, IL-2, IL-6, TNF-α, IL-18, sTNF-R1, and sTNF-R2), and intermittent hypoxia-induced oxidative stress." (PMID 41156291, 2025). "Previous studies have also reported elevated levels of IL-2 and IL-1β upon improved sleep and an elevation in IL-10 levels upon sleep disorders." (PMID 37139438, 2023). "The results showed that IL-2 × moderate occupational stress (OR = 0.778, 95% CI: 0.778–0.942) and IL-2 × non-mental disorders (OR = 0.398, 95% CI: 0.398–0.468) were protective factors for the occurrence of sleep disorders when compared with high occupational stress and mental disorders." (PMID 36245869, 2022). "The effects of IL-2 × low occupational stress, IL-2 × moderate occupational stress and IL-2 × non-mental disorders on sleep disorders were analyzed." (PMID 36245869, 2022). "Occupational stress had a direct positive predictive effect on mental disorder (β = 0.25), and sleep disorder had a direct negative predictive effect on IL-2 concentration (β = −0.21)." (PMID 36245869, 2022).
stable angina (6 papers, 2016 to 2025). "It has been shown that plasma concentrations of cytokines produced by Th1 (IFN-γ and IL-2) were significantly higher than those synthesized by Th2 lymphocytes (IL-10) in patients with ACS when compared to patients with stable angina." (PMID 27563892, 2016). "For instance, IL-2 is highly expressed in atherosclerotic plaques, and its concentration has been found to be increased in CAD cases especially in unstable angina subjects." (PMID 36672997, 2023). "Patients with stable angina were observed to have significantly higher IL-2 levels in the plasma than patients with unstable angina, but not different than controls, while IL-2′s soluble receptor was higher in patients with stable angina than those with unstable angina and controls." (PMID 38256155, 2024). "Sixty patients with ACS (unstable angina, non-ST elevation myocardial infarction or ST elevation myocardial infarction) with high-sensitivity C reactive protein (hsCRP) levels >2 mg/L will be randomised to receive either 1.5×106 IU of low-dose IL-2 or placebo (1:1)." (PMID 36207050, 2022).
systemic sclerosis (6 papers, 2021 to 2025). A chronic disorder, possibly autoimmune, marked by excessive production of collagen which results in hardening and thickening of body tissues. "The polymorphisms identified in ACE2 (chrX_15596143), IL-18 (chr11_112014152), IL-18R1 (chr2_103013408), IFNGR1 (chr6_137519588), and IL-2 (chr4_123377482) genes can be considered predisposing factors for the onset of systemic sclerosis." (PMID 38675400, 2024). "When searching for “systemic sclerosis” and cytokines in the PubMed database, TGF-β had the highest number of hits, followed by IL-6, IL-4, tumor necrosis factor (TNF)-α, platelet-derived growth factor, IL-10, IL-13, IL-1, IL-2, and IL-17 indicating cytokines are related to the pathogenesis of SSc." (PMID 34064515, 2021). "Another study has revealed that administering a low dose of IL-2 per day selectively activates and expands Tregs in patients with systemic sclerosis (SSc) without activating Teffs, paving the groundwork for a Phase II efficacy trial (NCT01988506)." (PMID 39290699, 2024). "The TGF-β signaling pathway significantly influences inflammation by modulating Th cell differentiation and reducing JMJD3-mediated production of cytokines such as IL-2, IL-4, and IFN-γ, as evidenced in systemic sclerosis (SSc)." (PMID 39315124, 2024).
alopecia (5 papers, 2021 to 2025). Hair loss usually from the scalp. "The IL2 gene is related to hair follicle growth, and has been associated with hair loss (alopecia) in humans." (PMID 34679946, 2021). "As many low-dose IL-2 trials in SLE patients have reported improvement in skin rashes and alopecia, it would be highly informative for future studies to consider measuring tissue-specific Treg expansion where possible." (PMID 36399073, 2023). "The baseline levels of pro-inflammatory cytokines did not predict alopecia; in contrast, the concentration of IL-12, IL-2, IL-17, IFN-γ and TNF-α at 1 year was significantly increased in patients complaining alopecia." (PMID 36601115, 2022).
angiosarcoma (5 papers, 2012 to 2025). A malignant tumor arising from the endothelial cells of the blood vessels. "The case is a 76 years old woman who developed angiosarcoma on chronic lymphoedema 11 years after mastectomy treated by local and systemic injections of recombinant IL2, the patient lived 16 months." (PMID 25574331, 2014). "Interleukin-2 therapy was used in angiosarcoma, although results of clinical trials were not yet available." (PMID 25865224, 2015). "In reconsideration of these results, IL-2 and LAK immunotherapy did not contribute to the patient's prognosis, even though immunotherapy is usually effective for hemangiosarcoma." (PMID 23342252, 2012).
appendicitis (5 papers, 2015 to 2024). Acute inflammation of the vermiform appendix. "The aim of the present study was to evaluate how the Th1 and Th17-associated cytokines IL-1α, IL-1β, IL-2, IL-6, IL-10, IL-17A and tumor necrosis factor beta (TNF-β) are associated with the risk of complicated appendicitis in children." (PMID 38409170, 2024). "One patient (C8) died from multisystem organ failure following a prolonged hospitalization for appendicitis 227 weeks after stopping LD IL-2." (PMID 36189229, 2022). "This prospective cohort study aimed to evaluate the association between serum concentrations of the Th1-associated cytokines interleukin (IL)-1α, IL-1β, IL-2, IL-6, IL-10, IL-17A and tumor necrosis factor beta (TNF-β) and the risk of complicated appendicitis in children." (PMID 38409170, 2024). "High serum concentrations of IL-6 were associated with an increased risk of complicated appendicitis in children, whereas serum concentrations of IL-1α, IL-1β, IL-2, IL-10, IL-17A and TNF-β were not." (PMID 38409170, 2024). "PCT, Interleukin (IL)-6, IL-2, and D-dimer plasma levels are elevated at different levels in the course of acute appendicitis and may be of particular value in the diagnosis of acute appendicitis." (PMID 34828754, 2021).
bacterial pneumonia (5 papers, 2018 to 2025). Acute infection of the lung parenchyma caused by bacteria (e.g., Streptococcus pneumoniae, Haemophilus influenzae, Chlamydia pneumoniae, Mycoplasma pneumoniae, and Legionella pneumophila). "Previous studies have found that after infection with bacterial pneumonia, the concentrations of IL-2 and TNF-α in susceptible types were increased significantly and gradually decreased as inflammation declined." (PMID 37180342, 2023).